MIR6506 (microRNA 6506)
Synonyms: hsa-mir-6506
Gene: MicroRNA gene on chromosome 16 (15,611,030 to 15,611,095, reverse strand). Ensembl gene ENSG00000284184.
Homologues: Orthologues: chimpanzee MIR6506 (100% identical), macaque MIR6506 (100% identical).